MIA3 (MIA SH3 domain ER export factor 3)
Description:
Plays a role in the transport of cargos that are too large to fit into COPII-coated vesicles and require specific mechanisms to be incorporated into membrane-bound carriers and exported from the endoplasmic reticulum. This protein is required for collagen VII (COL7A1) secretion by loading COL7A1 into transport carriers. It may participate in cargo loading of COL7A1 at endoplasmic reticulum exit sites by binding to COPII coat subunits Sec23/24 and guiding SH3-bound COL7A1 into a growing carrier. Does not play a role in global protein secretion and is apparently specific to COL7A1 cargo loading. However, it may participate in secretion of other proteins in cells that do not secrete COL7A1. It is also specifically required for the secretion of lipoproteins by participating in their export from the endoplasmic reticulum. Required for correct assembly of COPII coat components at endoplasmic reticulum exit sites (ERES) and for the localization of SEC16A and membrane-bound ER-resident complexes consisting of MIA2 and PREB/SEC12 to ERES.
Synonyms: TANGO1; KIAA0268; TANGO; UNQ6077; FLJ39207; D320; ODCD2
Tractability: Antibody: UniProt predicts a signal peptide or a membrane-spanning region. PROTAC: ubiquitination databases record sites on it; its protein half-life has been measured.
Gene: Protein-coding gene on chromosome 1 (222,618,090 to 222,668,007, forward strand). Ensembl gene ENSG00000154305.
Subcellular location: Endoplasmic reticulum membrane
Subcellular location (Human Protein Atlas): Vesicles
Pathways (Reactome):
Metabolism of proteins: Post-translational protein phosphorylation; Regulation of Insulin-like Growth Factor (IGF) transport and uptake by Insulin-like Growth Factor Binding Proteins (IGFBPs)
Vesicle-mediated transport: Cargo concentration in the ER
Gene Ontology:
Molecular function: cargo receptor activity; protein binding
Biological process: cell migration involved in sprouting angiogenesis; cellular response to oxidised low-density lipoprotein particle stimulus; COPII vesicle coating; COPII-coated vesicle cargo loading; endoplasmic reticulum to Golgi vesicle-mediated transport; exocytosis; lipoprotein transport; negative regulation of cell adhesion; negative regulation of cell migration; negative regulation of leukocyte cell-cell adhesion; negative regulation of lymphocyte migration; positive regulation of leukocyte migration; protein transport; wound healing; protein secretion; vesicle cargo loading; system development
Cellular component: endoplasmic reticulum exit site; endoplasmic reticulum membrane; membrane; endoplasmic reticulum lumen
Genetic constraint (gnomAD): Loss-of-function variants: 73 observed, 160.98 expected, observed/expected ratio (o/e) 0.45, 90% interval 0.37 to 0.55. The upper end of that interval is the gene's LOEUF score, 0.55, which puts it in group 2 of 6, group 1 being the genes least tolerant of losing a copy. Missense variants: 1,978 observed, 2,197.1 expected, observed/expected ratio (o/e) 0.9, 90% interval 0.87 to 0.93. Synonymous variants: 702 observed, 775.06 expected, observed/expected ratio (o/e) 0.91, 90% interval 0.85 to 0.96.
Homologues: Orthologues: chimpanzee MIA3 (99% identical), macaque MIA3 (93% identical), dog MIA3 (74% identical), rabbit MIA3 (73% identical), pig MIA3 (66% identical), mouse Mia3 (64% identical), rat Mia3 (63% identical), guinea pig MIA3 (53% identical), tropical clawed frog mia3 (33% identical), Drosophila melanogaster Tango1 (13% identical). Paralogues in human: MIA2 (18% identical), CTAGE9 (11% identical), CTAGE4 (11% identical), CTAGE8 (11% identical), CTAGE15 (11% identical), CTAGE6 (11% identical), CTAGE1 (10% identical), SPZ1 (7% identical), OTOR (3% identical), MIA (2% identical).
Diseases named in the same sentence as MIA3 in open-access papers:
MIA3 is named in the same sentence as 54 diseases in open-access papers, as found by Europe PMC text mining. Sharing a sentence is not in itself a finding about the gene and the disease. The quoted sentences say what the papers report.
colorectal cancer (5 papers, 2017 to 2025). A primary or metastatic malignant neoplasm that affects the colon or rectum. "In contrast, there is limited evidence for miRNA regulation of MIA3 (the gene that encodes TANGO1) apart from miR-30a-5p and miR-222-3p in colorectal cancer cells, even though the roles of TANGO1 in collagen secretion have received much attention recently." (PMID 35445708, 2022). "MIA3 is an inhibitor in malignant melanoma and colorectal cancer and is a promoter of tumour growth in oral squamous cell carcinoma." (PMID 37948019, 2024). "In colorectal cancer, overexpression of the MIA3 gene inhibits the proliferation and migration capacity of colorectal cancer cells." (PMID 37948019, 2024). "In this study, we observed thatmiR-222 enhanced migration and invasion through MIA3 in colorectal cancer." (PMID 28855850, 2017). "The mechanism by which MIA3 influences the migration and invasion of colorectal cancer cells requires further study." (PMID 28855850, 2017). "On the contrary, two other in vitro studies have shown that delivery of exosomal miR-30a, miR-222, and miR-146a-5p could promote colorectal cancer cell stemness by targeting two tumor-suppressor targets, namely, MIA3 and NUMB, respectively." (PMID 36674525, 2023). "miR-30a and miR-222 were demonstrated to target MIA3, while miR-146a-5p was reported to be suppressing NUMB expression in colorectal cancer cells." (PMID 36674525, 2023).
hepatocellular carcinoma (5 papers, 2014 to 2024). A malignant tumor that arises from hepatocytes. "We aimed to explore the role and underlying molecular mechanisms of MIA3/TANGO1 in the growth and migration of hepatoma cells." (PMID 37948019, 2024). "We confirmed that MIA3 is upregulated at the mRNA and protein levels in tumour cells by real-time quantitative PCR (qRT-PCR) and Western blotting of human normal and hepatoma cell lines." (PMID 37948019, 2024). "MIA3 further promotes the growth, metastasis, and invasion of hepatoma cells by binding to the CHAC1 protein and promoting GSH degradation." (PMID 37948019, 2024). "MIA3, also known as TANGO, encodes melanoma inhibitory activity family member 3, which exhibits tumor suppressor properties in colon and hepatocellular carcinomas and in malignant melanoma." (PMID 24498386, 2014). "According to the analysis of The Cancer Genome Atlas (TCGA) database, MIA3 is expressed at higher levels in hepatocellular carcinoma (HCC) tissues than in normal tissues." (PMID 37948019, 2024). "MIA3 may become a new target for the diagnosis and treatment of hepatocellular carcinoma." (PMID 37948019, 2024). "In hepatocellular carcinoma (HCC), MIA3 is found to be overexpressed, promoting cancer cell proliferation, migration, and invasion while inhibiting apoptosis." (PMID 39534397, 2024). "For example, MIA3 has been shown to promote the degradation of GSH by binding to CHAC1, thus facilitating hepatocellular carcinoma progression." (PMID 39534397, 2024). "Therefore, the MIA3/CHAC1/GSH axis may be a new target for the diagnosis and treatment of hepatocellular carcinoma." (PMID 37948019, 2024).
melanoma (5 papers, 2014 to 2024). A malignant, usually aggressive tumor composed of atypical, neoplastic melanocytes. "Bioinformatics and the dual luciferase reporter assay revealed that miR-222 specifically targeted the 3′-UTR of melanoma inhibitory activity member 3 (MIA3), down-regulating its expression at the protein level." (PMID 28855850, 2017).
atherosclerosis (4 papers, 2017 to 2023). A disease characterized by the build-up of fatty material and calcium deposition in the arterial wall resulting in partial or complete occlusion of the arterial lumen. "Recent genome-wide association studies reveal that single-nucleotide polymorphism (SNP) in MIA3 is associated with atherosclerosis-relevant VSMC phenotypes." (PMID 34858331, 2021). "A recent GAWS for 12 atherosclerosis-relevant phenotypes identified that the risk of single-nucleotide polymorphism (SNP) rs67180937 in the chromosome 1q41 locus was associated with lower VSMC MIA3 expression and lower proliferation." (PMID 34858331, 2021). "MIA3, also known as TANGO1, is a ubiquitously expressed protein that is involved in the export of collagen from the endoplasmic reticulum as well as angiogenesis and leukocyte migration, a phenomenon that has been linked to atherosclerosis." (PMID 37762360, 2023). "SMAD3 and MIA3 are important for vascular stability and angiogenesis, fundamental processes for plaque development and atherosclerosis, although the mechanisms are not fully known." (PMID 28737528, 2017). "TFPI subsequently activates the PI3K/AKT pathway to upregulate MIA3/TANGO1, which can prevent the initiation of atherosclerosis by inhibiting monocyte adhesion to endothelia and transmigration of monocytes across the endothelial wall." (PMID 34440364, 2021).
insulin-dependent diabetes mellitus (4 papers, 2023 to 2025). "A homozygous variant in the MIA3 (OMIM: 613455), encoding the TANGO1 protein, has been identified in four sibs with ODCD alongside other systemic manifestations like insulin-dependent diabetes, hearing loss, obesity, and mild intellectual disability." (PMID 40119123, 2025). "Although the majority of cases were associated with biallelic variants in TRIP11, one study described a homozygous truncating variant in MIA3, encoding TANGO1, in four sibs with ODCD in association with insulin-dependent diabetes, hearing loss, obesity, and intellectual disability." (PMID 40119123, 2025).
myocardial infarction (3 papers, 2015 to 2021). Gross necrosis of the myocardium, as a result of interruption of the blood supply to the area, as in coronary thrombosis. "Genome-wide association studies (GWAS) have described an association between MIA3 rs17465637 A/C polymorphisms and CAD and myocardial infarction." (PMID 34858331, 2021).
coronary artery disease (2 papers, 2017 to 2022). "The genetic variants rs17465637 in MIA3, rs9818870 in MRAS, and rs17228212 in SMAD3 have been associated with coronary artery disease in GWA studies (P<5×10−8), although explaining only a small proportion of the coronary artery disease risk." (PMID 28737528, 2017).
dyslipidemia (2 papers, 2012 to 2013). "In addition, we reported an association between MIA3 rs17465637 A allele with the risk of CV events in RA patients with dyslipidemia." (PMID 24286297, 2013).
lung carcinoma (2 papers, 2023 to 2024). "While these findings suggest that MIA3 and CCL20 may be crucial in mechanisms through which T cells promote brain and bone metastasis in lung cancer, additional research is needed for confirmation." (PMID 38445456, 2024).
prostate carcinoma (2 papers, 2024 to 2025). A carcinoma that arises from epithelial cells of the prostate gland. "MIA3 is expressed in tumour tissues of prostate cancer patients, has high sensitivity and specificity; it can be used as a new diagnostic biomarker for prostate cancer." (PMID 37948019, 2024).
bladder urothelial carcinoma (1 paper, 2024). "MIA3 was upregulated in bladder urothelial carcinoma (BLCA) and downregulated in thyroid cancer (THCA) and renal chromophobic cell carcinoma (KICH)." (PMID 37948019, 2024).
colon cancer (1 paper, 2017). "A recent study showed that MIA3 is down-regulated or even lost in colon cancer and that its overexpression decreases the migration and invasion of CRC cells." (PMID 28855850, 2017). "To investigate the correlation between miR-222 and MIA3 expression, we analyzed the colon cancer tissue samples by RT-PCR and immunohistochemistry for miR-222 and MIA3, respectively." (PMID 28855850, 2017). "We are particularly interested in MIA3, which has been shown to be down-regulated or even lost in colon cancer, and it influences the migration and invasion of CRC cells." (PMID 28855850, 2017).
endothelial dysfunction (1 paper, 2023). In vascular diseases, endothelial dysfunction is a systemic pathological state of the endothelium (the inner lining of blood vessels) and can be broadly defined as an imbalance between vasodilating and vasoconstricting substances produced by (or acting on) the endothelium. "The role of the AIDA/MIA3 locus in CAD has been discussed in terms of endothelial dysfunction through AIDA; however, MIA3 is also implicated in the modulation of vascular smooth muscle cell behaviour." (PMID 37759455, 2023).
Hypercholesterolemia (1 paper, 2016). An increased concentration of cholesterol in the blood. "The same approach applied to hypercholesterolemia identified three genes also associated with MI: MIA3, CNNM2, and TRIB1; suggesting their role in MI could be mediated through lipid metabolism." (PMID 27640124, 2016). "Three individual genes (MIA3, CNNM2, and TRIB1) and 44 gene pairs overlap between MI and hypercholesterolemia." (PMID 27640124, 2016).
ischemic stroke (1 paper, 2019). A stroke disorder caused by obstruction of blood flow to the brain, due to thrombotic (local blood clot formation) or embolic (due to a blood clot or other material traveling from another site) event. "There were no significant genetic associations observed among rs17465637 (MIA3) or rs501120 (CXCL12) and future adverse CV events, including MI, ischemic stroke, CV death and major adverse cardiovascular events (MACEs)." (PMID 31804579, 2019).
liver cancer (1 paper, 2024). An epithelial or non-epithelial malignant neoplasm that arises from the liver. "We compared MIA3 expression in different types of tumour samples and corresponding normal samples using liver cancer sequencing data from the TCGA database." (PMID 37948019, 2024). "In this study, we found that the expression of the MIA3 gene in the tissues of liver cancer patients was increased through the mining of TCGA data, and immune infiltration analysis revealed that MIA3 was negatively correlated with immune cells in HCC." (PMID 37948019, 2024). "TCGA database analysis revealed high expression of MIA3 in liver cancer tissues." (PMID 37948019, 2024). "In terms of mechanism, overexpression of MIA3 increases CHAC1 expression and promotes glutathione degradation in HCC to further promote the occurrence and development of liver cancer." (PMID 37948019, 2024).
oral squamous cell carcinoma (1 paper, 2024). "In oral cancer, the expression of the MIA3 gene promotes the proliferation and migration ability of oral squamous cell carcinoma cells and inhibits apoptosis of cancer cells." (PMID 37948019, 2024).
cancer (6 papers, 2017 to 2025). A tumor composed of atypical neoplastic, often pleomorphic cells that invade other tissues. "MIA3, also known as TANGO1 (Golgi transporter component protein), is a membrane protein localized at the ER and is implicated in cancer development and progression." (PMID 39534397, 2024). "However, the mechanism of MIA3 regulation in cancer is unclear." (PMID 28855850, 2017). "These included multitrait colocalization at 6 loci with a consistent direction of effect between CAD and cancer (ABO, PGAP3, ANGPTL4, SREBF1, HAUS6, and SYNJ2BP) and 7 with an opposing direction (CDKN1A, RGS19, CALCRL, SF3A3, LAMC1, MYO9B, and MIA3)." (PMID 40874306, 2025). "MIA3 (melanoma inhibitory active protein 3)/TANGO1 (Golgi transporter component protein) plays an important role in the initiation, development, and metabolism of cancer." (PMID 37948019, 2024). "Furthermore, methylation patterns in SDMCs influenced the transcription of several genes (MEIS1, MIA3, PCDHAC2, SH3BP4, and ATP8B1) involved in well-known cancer-related pathways and cancer hallmarks (FDR < 0.05)." (PMID 36348462, 2022).
tumour (4 papers, 2020 to 2024). "Our experimental study found that tumour tissue cells had higher MIA3 expression than normal liver cells." (PMID 37948019, 2024). "MIA3 exerts tumour-promoting effects in HCC by binding to the CHAC1 protein and promoting glutathione biodegradation." (PMID 37948019, 2024). "In summary, the MIA3 expression level is positively correlated with the occurrence of HCC, indicating that MIA3 is a tumour promoter in HCC." (PMID 37948019, 2024). "The survival-related features identified by univariate Cox regression analysis were clinical stage (p < 0.001), pathologic grade (p = 0.001), tumour capsule status (p = 0.002), vascular invasion status (p < 0.001), and MIA3 expression (p < 0.001)." (PMID 37948019, 2024). "MIA3 is known to be involved in tumour cell invasion and migration." (PMID 38445456, 2024). "Among genes upregulated in this group, CBX7, MIA3 and KANK1 have been shown to have tumor suppressive activities including roles in inhibition of cellular motility/migration and/or proliferation, and induction of cell cycle arrest in various malignancies." (PMID 32310997, 2020).
skeletal dysplasia (2 papers, 2025). Any Mendelian diseases that affects growth and development of the skeleton. "Based on the phenotypes of previously reported patients with MIA3 variants, we might speculate the presence of a spectrum of skeletal dysplasias with variable severity and presentation." (PMID 40119123, 2025). "Moreover, we detected a novel biallelic loss of function variant c.2768T>G, p.(Leu923*) in the MIA3 gene in a fetus with a severe skeletal dysplasia phenotype." (PMID 40130161, 2025). "Our study suggests the presence of a phenotypic spectrum associated with MIA3 variants including ODCD with milder skeletal deformities, a classic ODCD with severe skeletal deformities, and a lethal skeletal dysplasia at the severe end of the spectrum." (PMID 40119123, 2025). "In conclusion, our study highlights the phenotypic spectrum associated with MIA3 variants which includes ODCD with mild skeletal phenotype and additional extra-skeletal features, intermediate classic ODCD, and a lethal skeletal dysplasia mimicking knockout animal models." (PMID 40119123, 2025).
MIA3 also shares sentences with these, for which no sentence is quoted: diabetes (6 papers); dentinogenesis imperfecta (4); Intellectual disability (4); breast carcinoma (2); hearing loss (2); Hepatic fibrosis (2); osteochondrodysplasia (2); bacterial infection (1); breast invasive carcinoma (1); chest infections (1); clear cell carcinoma of the kidney (1); collagenopathy (1); fetal hydrops (1); gastric cancer (1); head and neck squamous cell carcinoma (1); Hearing impairment (1); infection (1); liver cirrhosis (1); lung adenocarcinoma (1); lung squamous cell carcinoma (1); neuroblastoma (1); Obesity (1); odontochondrodysplasia (1); oesophageal cancer (1); Osteopenia (1); osteosarcoma (1); pancreatic insufficiency (1); Platyspondyly (1); pulpitis (1); renal chromophobic cell carcinoma (1).
A further 4 diseases each share a sentence with MIA3 in 1 paper.